KCNH2 (potassium voltage-gated channel subfamily H member 2)
Description:
Pore-forming (alpha) subunit of voltage-gated inwardly rectifying potassium channel. Channel properties are modulated by cAMP and subunit assembly. Characterized by unusual gating kinetics by producing relatively small outward currents during membrane depolarization and large inward currents during subsequent repolarization which reflect a rapid inactivation during depolarization and quick recovery from inactivation but slow deactivation (closing) during repolarization. Forms a stable complex with KCNE1 or KCNE2, and that this heteromultimerization regulates inward rectifier potassium channel activity. [Isoform A-USO]: Has no inward rectifier potassium channel activity by itself, but modulates channel characteristics by forming heterotetramers with other isoforms which are retained intracellularly and undergo ubiquitin-dependent degradation. [Isoform B-USO]: Has no inward rectifier potassium channel activity by itself, but modulates channel characteristics by forming heterotetramers with other isoforms which are retained intracellularly and undergo ubiquitin-dependent degradation.
Synonyms: ERG-1; H-ERG; hERG1; ERG1; HERG; Kv11.1; LQT2; SQT1
Tractability: Small molecule: an approved drug acts on it; a structure with a bound ligand is known; a high-quality ligand is known; it has a binding pocket of medium quality; it belongs to a druggable protein family. Antibody: UniProt places it where antibodies can reach, with high confidence; its Gene Ontology location is reachable by antibodies, with high confidence; UniProt predicts a signal peptide or a membrane-spanning region. PROTAC: ubiquitination databases record sites on it; a small molecule that binds it is known.
Target class: Potassium channels; Ion channel; Voltage-gated ion channel; Voltage-gated potassium channel
Safety:
Unwanted effects reported when the protein is acted on. In parentheses: how it was acted on, where the effect was seen, and who reports it.
prolongation of QT interval of ECG (inhibition; cardiovascular system; source: Bowes et al. (2012))
Reduced, survival (inhibition; source: AOP-Wiki)
Increased Mortality (source: AOP-Wiki)
Torsades de Point (source: ClinPGx)
Gene: Protein-coding gene on chromosome 7 (150,944,064 to 150,978,394, reverse strand). Ensembl gene ENSG00000055118.
Subcellular location: Cell membrane
Pathways (Reactome):
Muscle contraction: Phase 3 - rapid repolarisation
Neuronal System: Voltage gated Potassium channels
Gene Ontology:
Molecular function: delayed rectifier potassium channel activity; identical protein binding; inward rectifier potassium channel activity; protein binding; protein homodimerization activity; scaffold protein binding; transcription cis-regulatory region binding; ubiquitin protein ligase binding; voltage-gated potassium channel activity; voltage-gated potassium channel activity involved in ventricular cardiac muscle cell action potential repolarization; monoatomic ion channel activity
Biological process: cardiac muscle contraction; cellular response to xenobiotic stimulus; membrane depolarization during action potential; membrane repolarization; membrane repolarization during action potential; membrane repolarization during cardiac muscle cell action potential; membrane repolarization during ventricular cardiac muscle cell action potential; negative regulation of potassium ion export across plasma membrane; negative regulation of potassium ion transmembrane transport; positive regulation of DNA-templated transcription; positive regulation of potassium ion transmembrane transport; potassium ion export across plasma membrane; potassium ion homeostasis; potassium ion import across plasma membrane; potassium ion transmembrane transport; regulation of heart rate by cardiac conduction; regulation of membrane potential; regulation of membrane repolarization; regulation of potassium ion transmembrane transport; regulation of ventricular cardiac muscle cell membrane repolarization; ventricular cardiac muscle cell action potential; regulation of heart rate by hormone; monoatomic ion transport; potassium ion transport; transmembrane transport
Cellular component: cell surface; inward rectifier potassium channel complex; perinuclear region of cytoplasm; plasma membrane; voltage-gated potassium channel complex; membrane
Genetic constraint (gnomAD): Loss-of-function variants: 34 observed, 79.69 expected, observed/expected ratio (o/e) 0.43, 90% interval 0.32 to 0.57. The upper end of that interval is the gene's LOEUF score, 0.57, which puts it in group 2 of 6, group 1 being the genes least tolerant of losing a copy. Missense variants: 1,272 observed, 1,540.4 expected, observed/expected ratio (o/e) 0.83, 90% interval 0.79 to 0.87. Synonymous variants: 786 observed, 687.76 expected, observed/expected ratio (o/e) 1.14, 90% interval 1.08 to 1.21.
Gene-disease validity (ClinGen):
ClinGen rates the evidence that KCNH2 causes each of these diseases.
long QT syndrome (autosomal dominant): Definitive.
short QT syndrome (autosomal dominant): Definitive. A genetic disease of the electrical system of the heart that consists of a constellation of signs and symptoms, consisting of a short QT interval on an EKG (< 300 ms) that does not significantly change with heart rate, tall and peaked T waves, and a structurally normal heart.
Brugada syndrome (autosomal dominant): Disputed. A genetically heterogeneous condition characterized by complete or incomplete right bundle branch block accompanied by ST elevation in leads V1-V3.
Homologues: Orthologues: chimpanzee KCNH2 (99% identical), macaque KCNH2 (99% identical), dog KCNH2 (97% identical), mouse Kcnh2 (96% identical), pig KCNH2 (96% identical), rat Kcnh2 (94% identical), guinea pig KCNH2 (94% identical), rabbit KCNH2 (91% identical), tropical clawed frog kcnh6 (70% identical), zebrafish kcnh2a (62% identical), zebrafish KCNH2 (44% identical), Caenorhabditis elegans unc-103 (38% identical), and 10 more. Paralogues in human: KCNH7 (58% identical), KCNH6 (54% identical), KCNH4 (32% identical), KCNH8 (32% identical), KCNH3 (30% identical), KCNH1 (29% identical), KCNH5 (29% identical), HCN4 (16% identical), HCN2 (15% identical), HCN1 (14% identical), HCN3 (14% identical), CNGA2 (12% identical), and 5 more.
Diseases named in the same sentence as KCNH2 in open-access papers:
KCNH2 is named in the same sentence as 249 diseases in open-access papers, as found by Europe PMC text mining. Sharing a sentence is not in itself a finding about the gene and the disease. The quoted sentences say what the papers report.
Arrhythmia (186 papers, 2007 to 2026). Any cardiac rhythm other than the normal sinus rhythm. "Pathogenic KCNH2 variants are strongly associated with cardiac arrhythmias leading to increased risk of sudden cardiac death." (PMID 41981942, 2026). "Long QT syndrome type 2 (LQT2) is an arrythmia caused by loss-of-function mutations in KCNH2, leading to impaired Kv11.1 channel function." (PMID 40271129, 2025). "To model inherited cardiac arrhythmias we selected representative N588D and N588K missense mutations affecting the same codon in the hERG potassium channel gene KCNH2, which are reported to cause long (LQTS) and short (SQTS) QT syndromes, respectively." (PMID 38297132, 2024). "Differences in individual arrhythmia susceptibility are a pressing issue in exploring KCNH2 mutation-induced type 2 LQTS." (PMID 36792990, 2023). "The most notable example is the human voltage-gated potassium channel subfamily H member 2 (KCNH2, or hERG), which is linked to cardiac arrhythmias." (PMID 37296454, 2023). "KCNH2 encodes for the Ether-A-Go-Go-Related Protein 1, a potassium voltage-gated channel, involved in arrhythmia." (PMID 35246263, 2022). "More sophisticated model systems such as cardiac myocytes derived from stem cells will help further define the relationship between KCNH2 variants and arrhythmia risk." (PMID 34002542, 2021). "Nevertheless, it has been reported that USCs from a patient with a mild form of type 2 long QT syndrome can be reprogrammed in iPSCs that differentiate in functional cardiomyocytes recapitulating cardiac arrhythmia phenotypes caused by mutation in KCNH2 gene." (PMID 34744760, 2021). "In conclusion, we have established that genetically matched hiPSC-CMs can capture electrophysiological differences related to the KCNH2 mutation, with these differences also reflected in the occurrence of drug-induced arrhythmias." (PMID 33176122, 2020). "On the other hand, cardiac arrhythmias are due to blocking of KCNH2-encoded hERG/Kv11.1 potassium channel and prolonging the QT interval." (PMID 33603707, 2020). "In all patients, except two patients with KCNH2 mutation in T618I, life-threatening arrhythmias were suppressed." (PMID 31427960, 2019). "Several potassium voltage-gated channel subfamily H member 2 (KCNH2) mutations were identified in persons with drug-induced arrhythmias in a database of SRS for adverse drug reactions." (PMID 27723808, 2016). "The major new finding of this work is that the factor causing activation of the KCNH2 current is present in serum of patients with HF accompanied by cardiac arrhythmia." (PMID 21625547, 2011). "Carriership of KCNH2 p.(Lys897Thr), a common single-nucleotide polymorphism that has previously been described as a modifier gene/allele, can affect the clinic phenotype, acting as a susceptibility risk factor for arrhythmia." (PMID 39940965, 2025). "KCNH2 pore variants confer the highest risk of arrhythmias and seizures in people with LQT2." (PMID 40234944, 2025). "Thus, a KCNH2 variant linked to LQT2, and epilepsy-mediated electrical remodeling, likely synergistically increase the risk of arrhythmias and SUDEP." (PMID 35600076, 2022). "Thus, blocking hERG (KCNH2) channels results in cardiac arrhythmia, and a variety of KCNH2 mutations can cause congenital long QT syndrome." (PMID 36421807, 2022). "It was shown that even common genetic polymorphism in the KCNH2 gene may contribute significantly to the clinical appearance of cardiac arrhythmia in patients with KCNJ2 mutations, and may serve as a predictor of symptomatic arrhythmias." (PMID 35456365, 2022). "In this study, we investigated whether KCNH2-K897T can modify the electrophysiological phenotypes and susceptibility to drug-induced arrhythmias observed in two hiPSC models of KCNH2 mutations known to cause LQT2." (PMID 34992545, 2021).
Arrhythmia (continued). "Either acute and/or chronic changes in cardiac function due to seizures may increase susceptibility to cardiac arrhythmias in people with a “loss‐of‐function” KCNH2 variant to significantly increase SUDEP risk." (PMID 34002542, 2021). "On the contrary, in the mother, some other factors, including unknown genetic modifiers, could counteract the functional impairment of mutant channels, thereby protecting the asymptomatic KCNH2-p.C108Y mutation-positive subject from arrhythmia susceptibility." (PMID 28749435, 2017). "In addition to these mutations collected from published literature, we also submitted information on gene variants, including one possible novel pathogenic mutation in the KCNH2 splice site found in ten Chinese families with documented arrhythmias." (PMID 20809527, 2010). "In the disease neighbor of KCNH2 and Potassium, the top five diseases that are similar to AS include Long QT Syndrome, Arrhythmias, Cardiac, Heart Diseases, Atrial Fibrillation, and Ventricular Fibrillation." (PMID 39832275, 2025). "Arrhythmia predisposition variants were found in KCNQ1 (n = 11, 0.28%), KCNH2 (n = 2, 0.05%), and SCN5A (n = 5, 0.13%) genes." (PMID 40332002, 2025). "For example, sotalol is recognized for its efficacy in treating various cardiac arrhythmias by targeting KCNH2 (hERG) channels." (PMID 39954672, 2025). "This discovery broadens our exploration of the KCNH2 gene in cardiac arrhythmias, highlighting the intricate genetic dynamics behind Long QT syndrome." (PMID 38873110, 2024). "Reduced IKr from either off-target pharmacological block or loss-of-function KCNH2 variants causes the cardiac disorder long QT syndrome (LQTS) and increases the risk for cardiac arrhythmia, syncope, and sudden cardiac death." (PMID 36496073, 2023). "We validated and optimized the NGS platform with a subset of 46 patients by comparison with Sanger sequencing of coding exons of major arrhythmia risk-genes (KCNQ1, KCNH2, SCN5A, KCNE1, KCNE2, RYR2)." (PMID 31337358, 2019). "TargetScan indicated that some arrhythmia-related mRNA encoding K channels, such as KCNQ1 and KCNH2, as possible targets of miR-133." (PMID 29843720, 2018). "Many drugs used for non-cardiovascular and cardiovascular purposes, such as sotalol, have the side effect of prolonging cardiac repolarization, which can trigger life-threatening cardiac arrhythmias by inhibiting the potassium-channel IKr (KCNH2)." (PMID 28800628, 2017). "Since the dominant action of class III antiarrhythmic agents is to lengthen the APD by a reduction of IKr, it is thought that the therapeutic effect of the agents against arrhythmia in the study subjects is manifested by offsetting oversupplied KCNH2 currents." (PMID 21625547, 2011). "We have also screened 10 Chinese families with various clinical arrhythmias, including 3 with LQTS, 2 with Brugada syndrome, 3 with sudden death syndrome, and 2 with Sick Sinus syndrome for mutations in KCNQ1, KCNH2, SCN5A, KCNE1 and KCNE2." (PMID 20809527, 2010). "KCNQ1 and KCNH2 are the two most common potassium channel genes causing long QT syndrome (LQTS), an inherited cardiac arrhythmia featured by QT prolongation and increased risks of developing torsade de pointes and sudden death." (PMID 18808722, 2008). "Because these proteins also control cardiac electrophysiology, variants in their encoding genes (KCNH2, CACNA1C) may increase arrhythmia and SCD risk." (PMID 37005595, 2023). "Additionally, variants found in individuals of the cardiogenetics cohort were in genes: MYBPC3 and KCNH2, both consistent with the pathologies investigated: Arrhythmia and Hypertrophic cardiomyopathy." (PMID 35087072, 2022). "On the basis of the data collected in this study, we may speculate that the presence of KCNH2-p.C108Y, together with three KCNE1-p.G38S alleles, could lead to an increased risk of developing cardiac arrhythmias due to the prolongation of the QT interval." (PMID 28749435, 2017).
Arrhythmia (continued). "In particular, the correction of the trafficking of KCNH2 (LQTS2) potassium channel through intracellular mechanisms restored hERG currents and reduced arrhythmia in LQTS2 patient-derived cardiomyocytes, also documenting the usefulness of iPSC-cardiomyocytes in LQTS2 modeling and drug testing." (PMID 27743118, 2016). "Furthermore, other studies have reported pathogenic mutations in BRCA1 in women without a family history of breast cancer and pathogenic mutations in SCN5A or KCNH2 in patients without phenotypic and electrophysiological evidence of cardiac arrhythmias." (PMID 32272925, 2020). "Mutation in the human ether-a-go-go-related gene (hERG or KCNH2) is responsible for reducing the rapidly activating component of the delayed rectifier potassium current (IKr), which can prolong the QT interval and induce arrhythmia (Type 2 Long QT syndrome, LQT2)." (PMID 23840331, 2013). "This work adds to the growing set of arrhythmia genes previously assayed by multiplexed assays for either the full protein (KCNJ2, calmodulin) or a portion of the protein (SCN5A, KCNH2)." (PMID 38816749, 2024). "KCNQ1/KCNH2 suppression-and-replacement, SCN5A base editing, and structural protein restoration via PKP2 and TMEM43 have each demonstrated capacity to re-establish electrophysiological stability in arrhythmia models." (PMID 42193469, 2026). "To this end, we determined the effects of the sEHI trans-4-[4-(3-adamantan-1-yl-ureido)-cyclohexyloxy]-benzoic acid (t-AUCB) on the expression of miR-133, its target arrhythmia–related genes (KCNQ1 and KCNH2), and serum response factor (SRF), an important transcriptional factor in cardiomyocytes." (PMID 29843720, 2018).